EDN1 (endothelin 1)
Diseases named in the same sentence as EDN1 in open-access papers (continued):
Sharing a sentence is not in itself a finding about the gene and the disease.
Hypertension (continued). "The serum level of endothelin-1 has been studied as a potential risk marker for adverse cardiovascular events (atherosclerosis, CAD, arterial hypertension, myocardial infarction, heart failure, increased left atrial diameter and left ventricular mass)." (PMID 37760823, 2023). "Physiological dysfunction of the endothelium promotes Endothelin-1 (ET-1) production, which further induces hypertension and proteinuria and inhibits the release of renin." (PMID 37368592, 2023). "Sex hormones are thought to play a modifying role in vascular function in hypertension through influencing endothelium-derived contracting factors such as endothelin-1, as well as nitric oxide production." (PMID 37484578, 2023). "The prohypertensive and inflammatory factors including Angiotensin II (Ang II), Tumor necrosis factor (TNF), aldosterone, growth factors, salt, sources from poor diet, and endothelin 1 (ET-1) are misregulated in hypertension and interact with NADPH oxidases." (PMID 37510117, 2023). "The pathogenesis of hypertension is not fully understood; endothelin 1 (EDN1) is involved in developing essential hypertension." (PMID 36942826, 2023). "The role of endothelin-1 (ET-1) in the progression of chronic kidney disease and the development of hypertension is relatively well known." (PMID 38068435, 2023). "Inhibiting TNF-α in RUPP rats attenuated hypertension, Endothelin-1, oxidative stress, and NK cell activation." (PMID 36909242, 2023). "The inflammatory corpuscles endothelin-1, angiotensin-2, and aldosterone are activated in patients with diabetes mellitus complicated by hypertension." (PMID 37599328, 2023). "Endothelin-1 is considered a predictor of adverse clinical outcomes in HF and plays a key role in many aspects of cardiac physiology and pathology, such as hypertension, cardiac contractility, and cardiac remodeling." (PMID 37198662, 2023). "This implies that endothelin-1 is a potential common pathway in which placental factors exert their effects on the maternal vasculature to induce vasoconstriction and hypertension [31••]." (PMID 37043097, 2023). "Despite having their blood pressure under control, the hypertension group showed higher levels of Endothelin 1 in comparison to the reference group." (PMID 35626723, 2022). "Endothelin-1 is a potent vasoconstrictor and pro-inflammatory protein and is an important contributor to the pathogenesis of hypertension, atherosclerosis, hypertrophy, and diabetes." (PMID 35663309, 2022). "Other researchers, based on the results of the conducted studies, suggested an increased expression of the endothelin-1 gene, both among patients with coronary artery disease, hypertension, and acute coronary syndrome, compared to healthy subjects." (PMID 35742539, 2022). "A separate GWAS suggested that phosphatase and actin regulator protein 1 (PHACTR1) and EDN1 (upstream of PHACTR1) are risk factors in five vascular diseases, including CAD, migraine, cervical artery dissection, fibromuscular dysplasia, and hypertension." (PMID 36046789, 2022). "Endothelin-1 is a potent vasoconstrictor that is involved in the implication of hypertension and atherosclerosis." (PMID 36434695, 2022). "The level and activity of eNOs is thought to be another factor involved in VEGF receptor inhibitor-related hypertension and endothelin-1 dysfunction." (PMID 35566115, 2022). "To test it, we analysed the levels of proteins relevant for both hypertension (Endothelin 1) and proteostasis (Ubiquitin and Clusterin), and their putative associations with the different forms of protein aggregates (oligomers and fibrils)." (PMID 35626723, 2022). "Endothelin-1 is a potent vasoconstrictor and has been shown to be involved in the development of atherosclerosis, hypertension, microvascular dysfunction in diabetes, stroke etc.." (PMID 35012642, 2022).
Hypertension (continued). "Rosiglitazone, a peroxisome proliferator activator receptor gamma (PPARγ) agonist, targets adipose tissue and has been shown to reduce endothelin-1 and attenuate hypertension as well as renal inflammation and injury in SLE mice model." (PMID 35770194, 2022). "Angiotensin receptor 1 agonistic autoantibodies increase oxidative stress and the secretion of endothelin 1 (ET1), a potent vasoconstrictor, contributing to hypertension." (PMID 35756742, 2022). "Here, we found the significant association of ADM, EDN1, ANGPTL4, USP8, NFIL3, MSR1, and CEBPD genes with hypertension." (PMID 35205232, 2022). "EDN1 has been involved in several cardiovascular disorders, including high blood pressure and pulmonary hypertension." (PMID 36620618, 2022). "This study investigates the effect of endothelin-1 (Lys198Asn/rs5370) and ECE (rs212526 C/T) gene polymorphisms with essential hypertension (EH) among Malay ethnics." (PMID 35645613, 2022). "In further research, 17-alpha-hydroxyprogesterone caproate was proved to blunt inflammatory cytokine secretion, hypertension, and renal endothelin-1 in a pregnant rat model of PE." (PMID 34732210, 2021). "IGF-1 regulates Endothelin-1 (ET-1), which has been found to have an important role in vascular hypertrophy and proliferation, leading to hypertension." (PMID 34198576, 2021). "Non-refractory primary obstetric APS IgG with β2GPI decreased NO bioavailability and VEGF production but increased endothelin-1 generation, which explains one of the triggering mechanisms of thrombosis and pregnancy morbidity and hypertension." (PMID 34925061, 2021). "Endothelin-1 is a potent vasoconstrictor secreted by vascular endothelial cells and has been long thought to play a role in the development of the hypertension component of the metabolic syndrome." (PMID 34966295, 2021). "Hypertension is a well-known side effect of rhEPO that can develop due to increase in the cardiac output, systemic resistance, and increased level of endothelin-1 and constrictor prostanoids." (PMID 33628672, 2021). "Hypertension and other cardiovascular diseases that often develop into HF are known to increase levels of endothelin-1 and angiotensin-II." (PMID 35002765, 2021). "In much the same way, monocytes minimise host stress by upregulating Ednra, which can scavenge endothelin-1 to prevent vasoconstriction and hypertension, and they increase expression of Vegfa to promote angiogenesis." (PMID 33752799, 2021). "For example, quercetin weakens the hypertension induced by uterine perfusion pressure in pregnant rats by reducing the levels of endothelin 1 (ET-1) and endothelin receptor type A (ET-A)." (PMID 34204038, 2021). "Nyberg M, Mortensen SP, Hellsten Y. Physical activity opposes the age-related increase in skeletal muscle and plasma endothelin-1 levels and normalizes plasma endothelin-1 levels in individuals with essential hypertension." (PMID 34008818, 2021). "Physiological dysfunction in the endothelium triggers the production of endothelin-1 (ET-1), which further induces hypertension and proteinuria and suppresses renin release." (PMID 32599856, 2020). "Su-induced arterial hypertension has also been related to an increase in endothelin-1 (ET-1) levels, and the administration with the ET-1 receptor antagonist macitentan showed attenuation in the elevation of blood pressure." (PMID 32698382, 2020). "This pathway is stimulated by the secreted factor endothelin 1 (EDN1) and the renin-angiotensin pathway ligand angiotensin II (causing cardiac hypertrophy in response to high blood pressure)." (PMID 32946788, 2020). "Reactive oxygen species (ROS) contribute to hypertension and vasoconstriction with Ang II or endothelin 1 (ET-1)." (PMID 31234522, 2019). "Endothelin-1 (ET-1) is a potential contributor to sex differences in the pathophysiology of hypertension." (PMID 30606254, 2019).
Hypertension (continued). "They observed that women with PE had an increased frequency of the T-5665 allele and circulating ET-1 levels, and maternal EDN1 genotype was correlated with the severity of hypertension in PE." (PMID 34268502, 2019). "Hypertension-induced shear stress can induce endothelium-derived vasoconstrictors such as endothelin-1 and angiotensin II." (PMID 31252672, 2019). "Endothelin-1 (ET-1) is an important modulator of the vascular tone and a proinflammatory molecule that contributes to the vascular damage observed in hypertension." (PMID 31712626, 2019). "An increase in the molecular coupling between inositol 1,4,5-trisphosphate receptor (IP3R) and TRPC3 augments endothelin-1- (ET-1-) induced vasoconstriction during hypertension." (PMID 31871548, 2019). "Among them, angiotensin II and endothelin-1 actively contribute to the pathogenesis of hypertension and its complications." (PMID 31357464, 2019). "An imbalance between vasodilating and vasoconstricting molecules, such as nitric oxide and endothelin-1, respectively, contributes to the pathogenesis of hypertension and its complications." (PMID 29772657, 2018). "On the other hand, secretion of endothelin-1, a vasoactive peptide involved in the pathophysiology of many cardiovascular diseases such as hypertension, atherosclerosis, and hypercholesterolemia, is dependent on the intracellular calcium concentration." (PMID 30427893, 2018). "Increased levels of endothelin-1 and erythropoietin have been suggested as possible factors of GC-induced hypertension." (PMID 30261581, 2018). "The goal of this study is to elucidate the role of Endothelin-1 (ET-1) in aortic stiffening-induced hypertension through ETA receptor activation." (PMID 29449619, 2018). "It has also been described that high blood pressure correlates with endothelin-1 concentrations, reflecting the modulatory pathway of blood pressure." (PMID 30544795, 2018). "One possibility is through regulating the function of endothelin-1 and altering the properties of vascular smooth muscle, which lead to the development of hypertension and atherosclerosis." (PMID 28804718, 2017). "Several experimental models of hypertension, atherosclerosis and diabetes are characterised by elevated levels of circulating ET-1 (Endothelin-1)." (PMID 32962323, 2017). "Because endothelin-1 is known to be a potent vasoconstrictor and mitogen it likely plays a role in the development of hypertension." (PMID 28344559, 2017). "In view of the role of hypertension on the progression of CKD in ADPKD, the gene polymorphisms of EDN1 are of great interest." (PMID 28197493, 2016). "These events can be induced by vasoactive agents, such as angiotensin II, endothelin-1, and aldosterone, which are increased in the vasculature during aging and hypertension." (PMID 27118293, 2016). "TNF-α have been shown to directly stimulate endothelial cells in culture to secrete endothelin 1 and cell adhesion molecules which would attract leukocytes to adhere to vascular tissues and play a role in edema and hypertension." (PMID 26113950, 2015). "EDN1 has been identified as a strong candidate for involvement in cardiovascular diseases, including essential hypertension." (PMID 26121692, 2015). "In contrast, in pathological chronic hyperleptinemia, the NO-mediated vasodilatory effects are impaired contributing to the development of hypertension, together with oxidative stress and overproduction of endothelin-1." (PMID 24499246, 2014). "Leptin is currently thought to contribute to systemic hypertension by a combination of mechanisms including sympathetic nervous system activation, overproduction of endothelin-1 and decreased release of NO." (PMID 24499246, 2014). "The results are compatible with the notion of abnormal pulmonary endothelial function involving leptin and endothelin-1 control in systemic hypertension." (PMID 24499246, 2014).
Hypertension (continued). "Edn1 over-expression in mice leads to development of systemic hypertension with altered vascular reactivity." (PMID 24722050, 2014). "Both phenotypes are characterized by augmented production of endothelin-1 (ET-1), suggesting a role for ET-1 in anti-angiogenic hypertension." (PMID 24632840, 2014). "We have developed a mutant strain of mice that do not produce both enzymes and found that these mice rapidly develop high blood pressure and show a reduced degradation rate of endothelin-1." (PMID 24586188, 2014). "Thus we determined whether the T323C polymorphism (rs5333) of endothelin type A (ETA) receptor, a predominant receptor evoking potent vasoconstrictive action of endothelin-1, contributes to susceptibility to IR-associated hypertension in 1694 subjects of Chinese and Japanese origins." (PMID 24348460, 2013). "Endothelin‐1 (ET‐1) is known to contribute to the renal hypertension observed following treatment with calcineurin inhibitors such as CsA, and previous studies in rats have demonstrated ET‐1 plays a role in CsA‐induced hypertension." (PMID 24744855, 2013). "Endothelin-1 (EDN1) is a potent vasoconstrictor, it is overexpressed in the vasculature in hypertension, and it is able to increase vascular growth." (PMID 24174980, 2013). "Certain hormones can be upregulated in metabolic disease, such as endothelin-1 in hypertension, and excessive levels of endothelin-1 can reduce aerobic capacity of muscle, and impair metabolism, most likely through impaired blood flow." (PMID 24772374, 2013). "Over-expression of EDN1, a potent vasoconstrictor peptide derived by the endothelium, has been implied in the pathogenesis of artherosclerosis and hypertension." (PMID 23505419, 2013). "We investigated the effect of perindopril on pulse-wave velocity (as indicator of arterial elasticity) and endothelin-1 (ET-1) levels in black hypertensive patients." (PMID 22914998, 2012). "Other SNPs affecting cholesterol levels (EDN1 K198N; OMIM_ID # 131240), familial obesity (FAM71F1 E143K; rs6971091) and hypertension susceptibility (PPARFC1A, G482S; rs8192678 and CYP4A11, F434S; rs1126742) were also found in the genome." (PMID 22938532, 2012). "In human SV, hypertension stimulates endothelin-1 release, which not only affects vascular reactivity but also increases oxidative stress." (PMID 22164326, 2011). "Increased endothelin-1 levels are thought to exert a greater vasoconstrictive effect on the blood vessels, which contributes to the development of hypertension." (PMID 21479272, 2011). "High plasma endothelin-1 and elevated plasma rennin activity are believed to contribute to high prevalence of hypertension and cardiovascular disease in psoriasis." (PMID 21063523, 2010). "In recent years, an important role of endothelin-1 (ET-1) in vascular hypertrophy and proliferation, leading to vasculopathies including atherosclerosis and hypertension has been suggested." (PMID 22043200, 2010). "Candidates EDNRA, EDN1 and EDNRB function together in a regulatory pathway with endothelin-converting enzyme ECE1, which has been implicated in essential hypertension." (PMID 20886000, 2010). "In DOCA-salt hypertensive rats, TZD treatmentreduced endothelin-1 production and blunted radical oxygen species productionwith diminished hypertension progression and vascular remodeling." (PMID 19266048, 2008). "A naturally occurringantagonist of NO is the vasoconstrictor endothelin-1, which is involved inatherosclerosis and hypertension." (PMID 19266048, 2008). "Recently, aprocitentan, an endothelin-1 inhibitor, was approved to treat arterial hypertension." (PMID 41524047, 2025). "Hypertension-induced vascular dysfunction and vasoconstriction are also significantly influenced by gene expression changes involving angiotensin II (Ang II) and endothelin-1 (ET-1)." (PMID 40002822, 2025).
Hypertension (continued). "Additionally, tacrolimus changes endothelial function by raising the synthesis of endothelin-1 and decreasing the synthesis of nitric oxide (NO), which exacerbates hypertension and vascular dysfunction." (PMID 40028266, 2025). "Additionally, a high concentration of plasma endothelin-1 in normotensive individuals is related to the development of arterial hypertension." (PMID 40076930, 2025). "The high levels of atrial natriuretic peptide, brain natriuretic peptide, endothelin-1, and adrenomedulin may also contribute to hypertension in hyperthyroidism patients." (PMID 39967991, 2024). "It has been theorized that inhibitors of VEGF or the signaling of VEGF receptors (VEGFRs) induce hypertension via decreased production of vasodilators (nitric oxide, prostacyclin), increased production of vasoconstrictors (endothelin-1), and rarefaction of microvascular endothelial cells." (PMID 39180119, 2024). "Low concentrations of endothelin-1 are considered to maintain cardiovascular homeostasis, whereas the excessive production of this vasoactive hormone has been demonstrated to result in hypertension, cardiac hypertrophy and heart failure." (PMID 38786079, 2024). "Lead-related hypertension may also be associated with genes such as the M allele in the AGT gene and G allele carriers in the EDN1 gene." (PMID 39771076, 2024). "An increased expression of vasoconstrictor endothelin-1 (ET-1) is another cofactor and may contribute to hypertension." (PMID 36768635, 2023). "EDN1 is involved in different developmental stages of hypertension." (PMID 36942826, 2023). "It would be of interest to establish whether the mRNA for Edn1 is altered in the ECs of these arteries in the SHRs during the development of hypertension." (PMID 37511055, 2023). "Angiotensin II and endothelin-1 are the main vasoconstrictors in hypertension pathogenesis." (PMID 36164390, 2022). "This positive association with Endothelin 1 is not surprising, since excessive weight is a major cause of hypertension, and associations between Endothelin 1 and obesity have been reported." (PMID 35626723, 2022). "In our hypertension cases, the EDN1 gene was found to be over-regulated compared to control." (PMID 35205232, 2022). "Other evidence suggests that endothelin-1 may play a role in the development of hypertension among patients with psoriasis." (PMID 36012327, 2022). "Higher endothelin-1 levels may, thus, contribute to the development of hypertension, due to an increased vasoconstrictive action on the blood vessels." (PMID 36012327, 2022). "Endothelin-1 (ET-1) is a potent vasoconstrictor and regulator of sodium excretion that induces inflammation and oxidative stress, so endothelin receptor antagonists have been investigated as a treatment for hypertension." (PMID 35770194, 2022). "Endothelin-1 (ET-1) is a vasoconstrictor peptide with a role in hypertension and kidney injury." (PMID 35163697, 2022). "Some reports propose that changes in vasoactive molecules, such as reduced NO bioavailability 23, excessive oxidative stress 24, increased levels of angiotensin II and endothelin-1 25, 26, regulate endothelial function during the development of hypertension following CIH." (PMID 35673562, 2022). "It is possible that free radical stress is a common biochemical mechanism in hypertension, because other factors, such as angiotensin II (Ang II), endothelin-1 (ET-1), aldosterone (Aldo), western diet and salt (Na) induce activation of NADPH oxidases (Noxs) which are known to increase ROS." (PMID 36615704, 2022). "In addition, the activated renin-angiotensin-aldosterone system can induce high blood pressure as endothelin-1 production increases via genetic upregulation in the aorta." (PMID 35053252, 2022).